IL17A (interleukin 17A)
Diseases named in the same sentence as IL17A in open-access papers (continued):
Sharing a sentence is not in itself a finding about the gene and the disease.
psoriasis (continued). "Our results suggest that the IL-17A cytokine, which is a critical initiator of the pathogenesis of psoriasis, is sufficient to induce a psoriatic inflammatory response in a 3D skin model." (PMID 35745784, 2022). "The proinflammatory cytokines, generated by both immune cells and keratinocytes, such as TNF-α, IL-17A and IL-23, induce and aggravate the development of psoriasis." (PMID 35938153, 2022). "IL-17A mediates its effect through high cholesterol since lowering cholesterol inhibits cytokine signaling in psoriasis." (PMID 35586340, 2022). "IFNG transcripts were mostly expressed in lesional LP (median/section:4), IL13 (median/section:1.5) and IL17A (median/section:9) in AD and psoriasis, respectively, with an emphasized expression in upper skin layers." (PMID 36513651, 2022). "In psoriasis, the keratinocyte proliferation that leads to skin lesions is a response to increased IL-17A production by memory Tc17 cells under the control of IL-23, providing an explanation for the efficacy of ustekinumab in this disease." (PMID 35072168, 2022). "A 2D visualization of psoriasis RNA-seq datasets was unable to prove the relationship between IL-17A and IL-22, which indicated alternative sources of IL-22 such as Th22 or non-T cells rather than Th17 in psoriasis." (PMID 35911703, 2022). "The expression of TNF-α and IL-6 as well as IL-22, IL-23, and IL-17 family of cytokines (IL-17A, IL-17E, and IL-17F) was significantly increased in psoriasis skin lesions." (PMID 35663991, 2022). "Population PK models of diverse mAbs, including anti-IL17A mAbs (secukinumab and ixekizumab), using serum total PK data in psoriasis patients have been reported." (PMID 35548359, 2022). "Immunological mechanism of the centrality of IL-17A, the shooting target of the therapeutic “hierarchy,” have been identified as key drivers of psoriasis pathogenesis and psoriasis multimorbidity." (PMID 35340911, 2022). "In an animal model of imiquimod-induced psoriasis, resveratrol downregulated the production of proinflammatory cytokines such as IL-17-A, IL-19, and IL-23." (PMID 35163855, 2022). "For example, in mouse psoriasis models RORγt positive ILC3 account for the production of the proinflammatory IL-17A and the potent keratinocyte growth factor IL-22 and levels of this cell type are increased in human psoriatic skin." (PMID 35337918, 2022). "Previous studies have shown that the TNF-α and IL-23/IL-17A axis is the main driver of psoriasis, and the interaction between IL-17A and keratinocytes is a key issue in developing psoriasis." (PMID 36590975, 2022). "The development of IL-17A inhibitors was a major milestone in psoriasis therapy, either alone (Secukinumab and Brodalumab) or in association with IL-17F (Ixekizumab)." (PMID 35563587, 2022). "Targeting of IL-17A and/or its receptor is effective in treating psoriasis, and administration of secukinumab resolves plaque histopathology and reduces proinflammatory gene expression in patients with psoriasis." (PMID 35054813, 2022). "Our result coincided with the finding that IL-17A- and IL-22-producing T cells in the peripheral blood of psoriasis patients play a critical role in affecting dermal inflammation." (PMID 35629363, 2022). "An alternative option for the treatment of psoriasis is antibodies that directly interfere with the downstream Th17 pathway triggered by IL-23, resulting in increased release of IL-17A, -17F, -22, -26 and -29." (PMID 36552866, 2022). "Clinical studies have demonstrated that IL-17A inhibition with secukinumab is effective for clearing the skin of patients with psoriasis and has a favorable safety profile." (PMID 35843765, 2022). "For the treatment of psoriasis, the following three IL-17-related monoclonal antibodies have been registered: secukinumab, ixekizumab, which directly blocks IL-17A, and brodalumab, which blocks IL-17A receptors." (PMID 35163689, 2022).
psoriasis (continued). "Herein, we found serum levels of IL-12B (median: 6.16 vs. 9.03, p = 0.0194) and Th17 cytokines (IL-17A: median: 0.32 vs. 1.05, p = 0.0026; IL-22: median: 4.41 vs. 4.41, p = 0.0120) were increased in psoriasis patients." (PMID 36118416, 2022). "The cytokine interleukin 17a(IL-17a) is involved in pathogenesis of several immunoinflammatorydiseases, including psoriasis, psoriatic arthritis, and rheumatoidarthritis." (PMID 36105327, 2022). "A further relevant biologic in this context is ixekizumab, a humanised IgG4 monoclonal antibody that binds with high affinity to IL-17A/F heterodimers, thereby inhibiting the inflammatory processes involved in psoriasis." (PMID 36552866, 2022). "We determined the expression levels of IL-17A and IL-22 in TCRγδT cells in the spleens of psoriasis-like mice after treatment with DXM using flow cytometry." (PMID 35629363, 2022). "In clinical trials, the antibodies of IL-23p19, IL-23p40, IL-17A, and IL-17RA have shown promising efficacy in the treatment of many autoimmune diseases including psoriasis, ankylosing spondylitis, and multiple sclerosis." (PMID 35528611, 2022). "While this drug acts by antagonizing the IL-17A Receptor, CosentyxTM and TaltzTM antagonize the pro-inflammatory cytokine IL-17A, which plays a role in psoriasis and Psa." (PMID 36140426, 2022). "Th17 cells produce IL-17A, -17F, and -22, which are all known as highly inflammatory cytokines that induce the keratinocyte activation and proliferation seen in psoriasis." (PMID 35163689, 2022). "During the early onset of psoriasis, LL-37 initiates the immune pathway, which eventually activates T cell-expressing IL-17A subsets, such as Th17 cells." (PMID 35203707, 2022). "The increase of IL-17A and IL-22 in serum samples of psoriasis patients demonstrates that its pathogenesis is driven by the IL-23/IL-17A axis." (PMID 36591277, 2022). "As such, anti-IL17A-targeting drugs are now proposed to patients with severe psoriasis and psoriatic arthritis." (PMID 36396641, 2022). "IL-17A has been demonstrated to play an essential role in the development and maintenance of psoriasis." (PMID 35922852, 2022). "At present, most monoclonal antibody preparations were aimed at this mechanism and block downstream inflammatory mediators such as TNF and IL17A to treat psoriasis." (PMID 35265149, 2022). "At present, IL-17A related diseases have been studied, including rheumatoid arthritis, psoriasis, Crohn’s disease, atherosclerosis, periodontitis and so on." (PMID 35371044, 2022). "This is the first study to address the protein levels of IL-17A, IL-17F and their receptors in the skin of PsA patients with mild psoriasis (mean PASI score < 10) in comparison with HD skin." (PMID 35203534, 2022). "As a regenerating gene, REG3A was abundantly expressed in the lesional skin of psoriasis patients and in IL-17A-induced neonatal human epidermal keratinocytes (NHEKs); however, its expression was very low in differentiated NHEKs." (PMID 34811636, 2022). "These preliminary results suggest that the serum Claudin-1 as a potential biomarker and the relationship and possible regulatory interactions between IL-17A and Claudin-1 in psoriasis are distinguishable by age of onset." (PMID 35340911, 2022). "There are six isoforms of IL-17 (IL-17A–IL-17F), whereby IL-17A has the most prominent role in psoriasis pathogenesis." (PMID 35313642, 2022). "Herein, we structurally and functionally validated a self-assembled reconstructed skin equivalent (RSE) and developed an IL-17a-induced in vitro psoriasis-like model using a self-assembled RSE." (PMID 35745784, 2022). "IL-17A is considered, along with IL-23, the most important target of plaque psoriasis therapy and has been recognized as the critical effector cytokine in psoriasis." (PMID 36232430, 2022). "In those models, the keratinocytes stimulated with IL-17A exhibited psoriasis-like inflammatory responses." (PMID 35745784, 2022).
psoriasis (continued). "The mechanism of action of secukinumab in psoriasis focuses on targeting the IL-17A released from Th17 to block it from binding with IL-17R." (PMID 35203707, 2022). "Although, the PASI score was comparable between the two groups, the degree of IL-8 reduction was positively related to the PASI score (p = 0.03, r = 0.63), suggesting bioactive IL-17A is positively correlated with psoriasis disease activity." (PMID 36118416, 2022). "Accordingly, psoriasis can be efficiently treated with antibodies targeting cytokines of type 3 immunity, i.e., IL-17A or IL-239,10." (PMID 36513651, 2022). "In mouse psoriasis models, IL-17A released from skin-infiltrating T cells has been demonstrated to increase neutrophil recruitment." (PMID 35514987, 2022). "Then, we verified the results in psoriatic lesions and a psoriasis model in vitro by stimulating keratinocytes with IL-17A, IL-22, IL-1α, oncostatin M, and TNF-α (M5)." (PMID 35586566, 2022). "There are six known IL-17 family members including IL-17A, IL-17B, IL-17C, IL-17D, IL-17E, and IL-17F, with IL-17A and IL-17F being the best studied in psoriasis." (PMID 35008981, 2022). "Compound 1 also clearly inhibited the phosphorylation of STAT3, which regulates the expression of cytokines, and CCL20 chemokines in TNF-α /IL-17A/ IFN-γ induced the psoriasis condition." (PMID 36015080, 2022). "In general, the IL-17A cytokine has been used alone or in combination with other cytokines to simulate psoriasis-like inflammation in 2D cell culture systems." (PMID 35745784, 2022). "Secukinumab is an anti-interleukin (IL)-17A IgG1-κ monoclonal antibody approved for psoriasis, psoriatic arthritis, and ankylosing spondylitis." (PMID 36355537, 2022). "The combination of cytokines (TNFα and IL-17A) both being important targets in psoriasis development were utilized in vitro to activate and promote keratinocytes proliferation and inflammatory responses while examining the intervention with the test compounds." (PMID 36741386, 2022). "The levels of IL-17A, a pivotal psoriasis-related cytokine, were measured in the culture supernatants as well." (PMID 35563819, 2022). "Mutations in the TRAF3IP2 gene in psoriasis promotes the ability of NET to induce Th17 cells in peripheral blood mononuclear cells and the secretion of IL-17A." (PMID 36405690, 2022). "The neutralization of IL-17A interrupts this interaction and has been proven as a fast and efficacious therapy for psoriasis." (PMID 36614836, 2022). "There are reports that IL-17A antibody has been successfully used for psoriasis, an autoimmunity disease, but related to CVD as well." (PMID 36133421, 2022). "Pro-inflammatory IL-23/IL-17A axis plays a major role in the progression and perpetuation of psoriasis." (PMID 35464441, 2022). "In psoriasis, CD8+ TRM-producing IL-17A are considered to be one of the pathogenic skin populations involved in the pathogenesis of the disease." (PMID 35886201, 2022). "In accordance, the vascular dysfunction was closely related to neutrophil infiltration into the aortic vessel wall and serum IL-17A levels in a murine psoriasis model." (PMID 35401573, 2022). "We observed that—both in peripheral blood and in synovial fluid—PsA patients have a higher proportion of single-IL-17A cytokine-producing Tregs as compared to healthy controls and psoriasis patients." (PMID 36450783, 2022). "In line, single-cell RNASeq analysis of psoriasis also indicated few transcripts per IFNG or IL17A transcript-positive cells, with a median UMI count for IFNG or IL17A of 1 per CD4+ cell and 4 per CD8+ cell." (PMID 36513651, 2022). "Since that IL-17A and TNF-α are the key inflammatory cytokines in the pathogenesis of psoriasis, we used IL-17A and TNF-α to stimulate HaCaT cells and conducted an inflammatory psoriatic in vitro model." (PMID 35153790, 2022).
psoriasis (continued). "While, Secukinumab (CosentyxTM) is the first fully human monoclonal immunoglobulin G1κ antibody targeting human IL-17A, with indications for psoriasis, psoriatic arthritis, and ankylosing spondylitis." (PMID 36248896, 2022). "When the condition of psoriasis becomes complex, it is difficult to explain serum levels of IL-17A by the emerging complications." (PMID 35340911, 2022). "Yet, the therapeutic strategies of targeting IFN-γ or IL-17A for psoriasis and IBD still face several limitations to overcome." (PMID 36591260, 2022). "As in the 2D culture model, in this study, the IL-17A cytokine was used as a stimulator to induce psoriasis-like skin inflammation." (PMID 35745784, 2022). "Secukinumab and Ixekizumab were the first IL-17A monoclonal antibodies that were developed and established with great success in psoriasis treatment." (PMID 36614836, 2022). "Augmented levels of IL-17A have been reported in peripheral tissues and the central nervous system in some autoimmune and neurodegenerative disorders, such as psoriasis, rheumatoid arthritis and multiple sclerosis." (PMID 36312009, 2022). "Drugs that inhibit TNFa, IL‐17A and IL‐23 have shown the greatest clinical effectiveness in the treatment of patients with psoriasis, but the systemic immunosuppressive effect, the need for regular administration and the high cost limit their use." (PMID 35677925, 2022). "In summary, we provide knowledge about miRNA and circRNA dynamics during anti-IL-17A treatment in psoriasis." (PMID 36174034, 2022). "In this study, we optimized the IMQ-induced mouse model of psoriasis and developed a repeatable model with proper severity and stable pathogenesis for the determination of IL17A antagonists." (PMID 33509093, 2021). "In the present study, we demonstrated that IFN-γ/IL-17A/IL-22 stimulation induce psoriasis-like changes in human keratinocytes." (PMID 33986690, 2021). "Secukinumab is a human monoclonal antibody that targets and blocks interleukin 17A (IL-17A), exhibiting great efficacy in the treatment of psoriasis and psoriatic arthritis." (PMID 34103043, 2021). "The presence of IL-17A-producing CD8+ CD103+ TRMs in the epidermis has been found to contribute to the prognosis of psoriasis." (PMID 34445713, 2021). "Glycyrrhizin is a therapeutic substance that improves psoriasis by down-regulating IL-17A and INF-γ, and further inhibits the expression of IL-6, TNF-α, and CCL20 induced by IL-17A." (PMID 34044769, 2021). "On that account, the development of biologic agents represented by monoclonal antibodies that target and inhibit the expression of IL-17A have proven to grant outstanding clinical efficacy in the treatment of psoriasis." (PMID 34947847, 2021). "For example, activation of STAT3 by IL-22 is involved in the proliferation of keratinocytes, and activation of STAT3 by IL22 and IL-17A is involved in the induction of keratin 17, which is overexpressed in psoriasis." (PMID 34679602, 2021). "It is well-known that IL-17 cytokine family (produced by Th17 cells) is involved in inflammatory autoimmune-mediated diseases such as psoriasis, where tissue inflammation also occurs due to high expression of IL-17A and IL-17F." (PMID 34947847, 2021). "IL-17A is strongly associated with certain autoimmune diseases, such as psoriasis, rheumatoid arthritis, and Crohn’s disease, with FDA-approved inhibitors of IL-17A used in treatment of some of these conditions." (PMID 33824206, 2021). "Recently, IL-19 was suggested as an important mediator of the IL-23/IL-17 cascade in psoriasis, and IL-17A-induced expression of IL-19 in keratinocytes amplifies keratinocyte responses via auto-paracrine regulation." (PMID 34616394, 2021). "Our results suggest that serum IL-17A level can be used as an objective parameter to determine the severity of psoriasis." (PMID 33356031, 2021).
psoriasis (continued). "CD279/PD1 is expressed on IL-17A+ T cells in psoriasis lesions and its blockade ameliorates inflammation in the aldara-induced psoriasiform skin inflammation model." (PMID 34362923, 2021). "Recent analysis of the transcriptome profiling has led to the discovery of the pathophysiological connection between psoriasis and dyslipidemia via the IL-17A cytokine pathway." (PMID 34445769, 2021). "These elevated expression levels appeared consistent with previous studies that employed a similar IFN-γ/IL-17A/IL-22-induced psoriasis-like model in keratinocytes." (PMID 34834106, 2021). "In order to simulate the effect of IL-17A on keratinocytes in psoriasis, we treated HaCaT cells with 100 ng/mL IL-17A (IL-17A-HaCaT cells) for 48 h." (PMID 34044769, 2021). "After injection of LCN2 into imiquimod (IMQ)-induced psoriasis-like skin, the mRNA expression levels of IL17A, CXCL1, CCL20, S100A7, and other cytokines and chemokines increased, which supports our analysis results." (PMID 33613635, 2021). "IL-10, IL-17A, IL-17RA (interleukin 17A receptor), IL-23A (interleukin 23 subunit α) and IL-23R (interleukin 23 receptor) in the development of psoriasis." (PMID 34945130, 2021). "Significant upregulation of IL-17A, IL-19, IL-24, and Ki-67 in psoriasis was confirmed in another independent dataset." (PMID 34616394, 2021). "In recent years, drugs for psoriasis have been screened as target suppression of IL-17A, IL-23, and Janus kinase (JAK), such as ustekinumab, ixekizumab, and tofacitinib, which are well effective but expensive." (PMID 33981308, 2021). "Intradermal or subcutaneous injections of IL-23 contributed to a significant over-expression of TNF-α and IL-17A, leading to psoriasis-like inflammation." (PMID 34831296, 2021). "IL-19, along with other IL-20 subfamily cytokines such as IL-20 and IL-24, is induced by IL-17A and contributes especially to epidermal hyperplasia in psoriasis." (PMID 34616394, 2021). "Th17 cells, which are stimulated by IL-23, play a central role in psoriasis development through IL-17A and IL-22 production." (PMID 33483537, 2021). "Herein, we present three cases of oral candidiasis (OC) related to the use of an IL17A inhibitor for psoriasis." (PMID 35054170, 2021). "Nevertheless, Anti-IL17A treatment exerted inferior efficacy than glucocorticoids, indicating a “partial role” of IL17A signaling in IMQ induced psoriasis development." (PMID 33509093, 2021). "STAT3 mediates the signal of most cytokines in pathogenesis of psoriasis, including IL-23, IL-17A, IL-22." (PMID 34925011, 2021). "Up to date, Cosentyx (Novatis) and Taltz (Eli Lilly) are approved anti-IL17A monoclonal antibodies for clinical treatment of psoriasis, psoriatic arthritis and axial spondyloarthritis." (PMID 33509093, 2021). "We obtained a psoriasis-like phenotype of HPK with a combination of physiological concentrations of IL-17A, IL-22 and TNF-α (20 ng/mL each)." (PMID 33801280, 2021). "The pro-inflammatory cytokines, such as IL-6, TNF-α, IL-1β, IL-22, and IL-17A, have been reported to be up-regulated in psoriatic lesioned tissue and serum, and these cytokines likely drive the psoriasis pathogenesis." (PMID 33323018, 2021). "IL-17A targeting has been proven successful in various inflammatory dermatological conditions, including psoriasis and lupus erythematosus." (PMID 33968147, 2021). "This work aimed to evaluate the role of miRs (miR-4649-3p, miR-6867-5p, miR-4296, miR-210, and miR-1910-3p) that target the FOXP3 mRNA and IL-17A mRNA in psoriasis." (PMID 33356031, 2021). "Imiquimod-induced psoriasis mice model and TNF-α or IL-17A induced HaCAT cells, an experimental model in vitro for psoriasis, were constructed to explore the effect of BRD4 inhibition on psoriasis and the specific mechanism about MAPK pathway." (PMID 34674702, 2021). "We found that IL-17A and IL-36γ cooperate in promoting a psoriasis-like phenotype and infiltration of neutrophils." (PMID 34440590, 2021).